PHF14 (PHD finger protein 14)
Diseases named in the same sentence as PHF14 in open-access papers (continued):
Sharing a sentence is not in itself a finding about the gene and the disease.
cancer (continued). "The enhanced signal of PHF14 in cancer tissues is more prominent in nucleus, which is consistent with its potential role in epigenetic regulation and mitosis." (PMID 28160558, 2017). "The strong positive staining with purified anti-PHF14 antibodies was observed in tumor tissues, especially prominent in nucleus, while non-cancer tissues have little signal." (PMID 28160558, 2017). "Knocking down PHF14 suppressed cancer cell growth and carcinogenesis, while over-expressing PHF14 promoted cell proliferation." (PMID 28160558, 2017). "About 82% (58/71) of tumor tissues exhibited a significant increase in PHF14 expression (score ≥9, up to 16, P<0.001) compared with paired non-cancer lung tissues using an immunoreactive scoring method." (PMID 28160558, 2017). "Several independent cancer cohorts were recruited for studying the significance of PHF14 in carcinogenesis." (PMID 28160558, 2017). "Although the PHD finger protein is considered to be involved in chromatin-mediated transcriptional regulation, little is known about the function of PHF14 in cancer." (PMID 23833654, 2013). "Therefore, PHF14’s involvement in chromatin complex effects underscores its significance in oncogenesis and presents it as a potential target for cancer therapy." (PMID 38813086, 2024). "This interaction suggests a mechanism through which PHF14 may contribute to tumor immune escape, highlighting its importance in the context of immunology and cancer progression." (PMID 38813086, 2024). "Understanding PHF14’s influence on immune checkpoint pathways could enhance the efficacy of immune checkpoint inhibitors, offering new avenues for cancer immunotherapy." (PMID 38813086, 2024). "Therefore, multiple methods were used to study the relationship between cancer-related fibroblasts and PHF14 gene expression in various cancer types in TCGA, so as to better understand how PHF14 expression reacted tumor-infiltrating immune cells." (PMID 37007943, 2023). "Furthermore, based on PHF14 expression levels, human pan-cancer samples were divided into high and low expression groups, and the enrichment of signaling pathways in KEGG and the markers of the two groups were analyzed by GSEA." (PMID 37007943, 2023). "Compared to VHL, XIAP, and AHR, which were highly expressed in less than half of cancer types in TCGA, PHF14 may serve as a good candidate for pan-cancer usage over co-opted E3 ligases in terms of expression pattern." (PMID 37845222, 2023). "Several emerging studies have demonstrated that PHF14 expression is closely associated with the development of some cancers, but there is still no feasible pan-cancer analysis." (PMID 37007943, 2023). "Therefore, TCGA, CPTAC, and GEO databases were adopted to assess PHF14 expression, genetic alterations, survival prognosis or immune infiltration of 33 different cancer types." (PMID 37007943, 2023). "The expression level of PHF14 was significantly different between different types of tumors and adjacent normal tissues, and the expression or genetic alteration of PHF14 gene was closely related to the prognosis of most cancer patients." (PMID 37007943, 2023). "The heatmap data obtained from the TIMER2 online tool revealed that PHF14 and methyltransferase expression levels positively correlated with most TCGA tumor types, suggesting that PHF14 can mediate tumorigenesis and progression through regulating human pan-cancer epigenetic status." (PMID 37007943, 2023). "Depletion of PHF14 inhibits cancer cell proliferation and tumorigenesis in lung cancer." (PMID 32596345, 2020). "PHF14 is consistently overexpressed in cancer cells in comparison with normal gastric mucosa cells." (PMID 32596345, 2020).
cancer (continued). "The roles of PHF14 in different types of cancers are contradictory." (PMID 31798343, 2019). "PHF14- or KIF4A-depletion alone notably impaired the proliferation of the cancer cells." (PMID 28160558, 2017). "It will be of great interest to recruit more patients with different cancer types to test whether PHF14 and KIF4A are co-overexpressed and co-activated in other cancer types." (PMID 28160558, 2017). "However, the biological function of PHF14 in tumors differs according to different cancer types." (PMID 31798343, 2019). "For example, PHD Finger Protein 14 (PHF14), interacting with TP5341, was highly expressed in over 70 percent of cancer types at transcriptomic and proteomic levels in tumors while lowly expressed in most normal tissues." (PMID 37845222, 2023). "Simultaneously, the highly expressed PHF14 was significantly relevant to poor PFS prognosis in KIRC, LGG, LUAD, and PAAD cancers." (PMID 37007943, 2023). "In addition, using the Kaplan-Meier plotter for survival analysis, the highly expressed PHF14 was relevant to a poor DFS prognosis in ACC, COAD, KIRC, LGG, LIHC, LUAD, MESO cancer patients, while TGCT was the opposite." (PMID 37007943, 2023). "Although the strong correlation between PHF14 and individual tumors has been gradually identified, how PHF14 expression interacts with carcinogenesis and clinical prognosis of multiple tumor types has not been comprehensively evaluated through pan-cancer analysis." (PMID 37007943, 2023).
tumor (14 papers, 2013 to 2025). "The association between PHF14 and immune checkpoints suggests a potential to modulate the tumor’s visibility to the immune system." (PMID 38813086, 2024). "Our results showed that PHF14 expression was inversely associated with the level of SMAD7 in tumor specimens with high DNMT3B expression, and by contrast, the correlation between the expression levels of PHF14 and SMAD7 was not significant in those expressing low DNMT3B." (PMID 37072414, 2023). "However, the tumor suppression effect in vivo caused by siLINC00612 was neglected when co-transfected with siLINC00612 + miR-590 inhibitor or siLINC00612 + Lv-PHF14." (PMID 30940184, 2019). "Further studies showed that PHF14’s expression is positively correlated with tumor immune checkpoint gene expression levels, indicating its significant role in modulating tumor immunity." (PMID 38813086, 2024). "By regulating the expression of immune checkpoint genes, PHF14 potentially influences the immune system’s ability to recognize and combat tumor cells." (PMID 38813086, 2024). "PHF14 protein were highly expressed in tumor tissues (KIRC, PAAD, and LIHC) compared to normal tissues." (PMID 37007943, 2023). "In recent years, several studies have revealed an association between PHF14 expression and decreased overall survival in STAD, BLCA, LUAD, GBM and LGG, while PHF14 overexpression suppressed the growth of tumor cells in CHOL and COAD." (PMID 37007943, 2023). "In this study, PHF14 co-expressed genes were analyzed for pathway enrichment to explore the mechanism of PHF14 gene in tumor." (PMID 37007943, 2023). "After finding the difference in the expression of PHF14 protein in normal and tumor tissues, we cultured tumor cell lines and corresponding normal cell lines in vitro." (PMID 37007943, 2023). "Nude mice, inoculated with PHF14 knockout SHSY-5Y cells developed earlier and larger tumors than control cell-inoculated mice and Sunitinib administration caused greater tumor suppression in mice harboring PHF-14 knockout than control SHSY-5Y cells." (PMID 36359362, 2022). "The subcutaneous xenograft experiment showed that tumors formed by cells knocking down PHF14 grow slower than those in of the shGFP group not only in tumor volume, but also in tumor weight." (PMID 32596345, 2020). "It is necessary to explore the role of PHF14 in various processes such as epigenetic regulation, chemoradiotherapy resistance, and tumor metabolism." (PMID 32596345, 2020). "The IHC results showed that PHF14 was less expressed in siLINC00612 tumor tissue than those in control, Lv-PHF14 and siLINC00612 + Lv-PHF14 tumor tissues." (PMID 30940184, 2019). "The mean weight of tumors generated by A431 PHF14 KD cells was 63.6% of that generated by A431-con cells assessed at the same time point, indicating that depletion of PHF14 can potently restrict tumor growth in vivo." (PMID 31040906, 2019). "The median overall survival of tumor bearing mice was prolonged from 32 days (n = 6) to 44.5 days (n = 4) after PHF14 was knocked down (P < 0.05)." (PMID 31798343, 2019). "Furthermore, PHF14 propels tumor progression in gastric cancer by modulating the AKT and ERK1/2 signaling pathways." (PMID 38813086, 2024). "In addition, the relationship between PHF14 expression level and different tumor pathological stages was investigated using the GEPIA2." (PMID 37007943, 2023). "Enrichment analysis of KEGG pathway revealed that “mRNA surveillance pathway” may be involved in the pathogenesis of tumor PHF14." (PMID 37007943, 2023). "Therefore, the relationship between PHF14 expression and survival in patients with different tumor types was further analyzed using the GEPIA2 tool." (PMID 37007943, 2023).
tumor (continued). "To characterize effects of PHF14 depletion on tumor growth in vivo, we inoculated PHF14 knockout (sgRNA-PHF14) SHSY-5Y cells and SHSY-5Y control cells subcutaneously into five-week-old male athymic nude mice (Nu/J, n = 10) at the density of 2 × 106 cells/animal." (PMID 36359362, 2022). "In nude mice xenografts, the tumor volume and mass could be significantly affected by modulation of miR-590 and PHF14 in T24 which subcutaneously injected to nude mice (P < 0.05)." (PMID 30940184, 2019). "Anchorage-independent growth of PHF14-knockdown tumor cells was strongly suppressed." (PMID 28160558, 2017). "Moreover, the growth of tumor cells with PHF14 knockout was significantly inhibited." (PMID 37007943, 2023). "Finally, the enrichment results of BP pathway revealed that, “RNA splicing,” “histone modification” and “chromatin remodeling” may all be involved in the pathogenesis of tumor PHF14." (PMID 37007943, 2023). "PHF14 may have multiple functions in gene regulation, cell proliferation, and tumor development." (PMID 28160558, 2017). "We pinpointed 8 human-derived genes (PHF14, PELP1, RPL7L1, HPRT1, RELN, RNU1-75P, RNU5A-8P, RNVU1-19), likely to represent tumor-specific signals as a signature combining these genes demonstrated high accuracy in assessing therapy response." (PMID 39337470, 2024). "Moreover, the correlation between PHF14 expression and immune checkpoint gene levels suggests a potential for PHD finger proteins to influence the tumor immune environment, offering insights into enhancing the efficacy of immunotherapeutic agents." (PMID 38813086, 2024). "Moreover, our data revealed that PHF14 expression correlates with lowered SMAD7 level and shorter survival of LAD patients, and importantly that SMAD7 methylation level of circulating tumor DNA (ctDNA) can potentially be used for prognosis prediction." (PMID 37072414, 2023). "As a result, two nude mice in PHF14 silencing group were excluded because no tumor was found after euthanized." (PMID 31798343, 2019).
adenocarcinoma (1 paper, 2017). A common cancer characterized by the presence of malignant glandular cells. "Analysis of the correlation between the overexpression of PHF14 and the clinicopathologic features of NSCLC revealed that high expression of PHF14 (score > 12) was correlated with adenocarcinoma (P<0.01)." (PMID 28160558, 2017).
PHF14 also shares sentences with these, for which no sentence is quoted: lung adenocarcinoma (4 papers); autism (1); breast carcinoma (1); colon adenocarcinoma (1); head and neck squamous cell carcinoma (1); neurodegenerative disease (1); neurodevelopmental disorder (1); ovarian carcinoma (1); pheochromocytoma (1); rectal cancer (1); rectum tumors (1); renal cell carcinoma (1); skin cancer (1); skin cutaneous melanoma (1); thyroid carcinoma (1); uterine corpus endometrial carcinoma (1).